METTL14 (methyltransferase 14, N6-adenosine-methyltransferase non-catalytic subunit)
Diseases named in the same sentence as METTL14 in open-access papers (continued):
Sharing a sentence is not in itself a finding about the gene and the disease.
tumor (continued). "METTL14 promotes tumor progression by binding to THBS1 3’ UTR region and decreasing its expression." (PMID 35354789, 2022). "Furthermore, chorioallantoic membrane assay revealed significant tumor size reduction after knockdown of METTL14 in vivo." (PMID 35048498, 2022). "Here, we review the role methyltransferase METTL14 in tumor occurrence and expansion." (PMID 34904301, 2022). "In addition, METTL14-deficient macrophages significantly downregulated the global m6A level to reduce CD8+ T cells and increase dysfunctional T cells, promoting tumor growth." (PMID 35331234, 2022). "The data indicated that METTL14 overexpression repressed the tumor volumes and weight." (PMID 35251990, 2022). "Ours is the first study to demonstrate that METTL14 has an oncogenic role and favours migration and invasion as a tumour promoter in CM, and thus could serve as a novel biomarker." (PMID 36264762, 2022). "In addition, to validate the function of METTL14 for tumor growth in vivo, we subcutaneously injected stably transfected METTL14 knockdown DU145 cell lines in nude mice." (PMID 35354789, 2022). "FTO, RBMX, METTL3, and METTL14, have been demonstrated to be tumor proto-oncogenes or biomarkers through m6A, with METTL3 serving as a pathological diagnostic index and potential therapeutic target for ESCA, and with RBMX encoding HNRNPG to affect m6A, also a member of the hnRNPs family." (PMID 36195940, 2022). "Next, we investigated the molecular mechanism by which METTL14 regulates BCa tumor metastasis." (PMID 36288387, 2022). "Moreover, hematoxylin and eosin (H&E) staining showed a higher number of metastatic tumor nodules in the lungs of the METTL14 knockdown group than in the control group." (PMID 35036065, 2022). "Our study confirmed reports that METTL14 acts as a tumor suppressor in HCC." (PMID 35223847, 2022). "To elucidate whether METTl14 suppressed in vivo tumor growth, we established a METTl14 or NC stably transfected SGC-7901 cell line, which was then subcutaneously injected into the flank of nude mice." (PMID 35164771, 2022). "While METTL14, WTAP, METTL3, ALKBH5, and YTHDC2 had lower expression in high risk group, indicating that they might be tumor suppressor." (PMID 35077391, 2022). "Moreover, levels of METTL14 were negatively correlated to the tumor stage, grade, and nodal metastasis status." (PMID 35036065, 2022). "Given the fact that METTL14 expression is decreased in GC tissues, we speculated that METTL14 may function as a tumor suppressor in GC." (PMID 35164771, 2022). "In addition, the expression of METTL14 was negatively correlated to the prognosis, stage, and ccRCC tumor grade." (PMID 35036065, 2022). "Interestingly, METTL14 expression affected the immune activity of the tumor microenvironment, thus providing additional insight into the therapeutics of PCa." (PMID 35559023, 2022). "In renal cell carcinoma, the down-regulation of METTL14 can promote tumor cells metastasis." (PMID 35022030, 2022). "Additionally, METTL14‐KD tumors disclosed a lower number of vessels at tumor periphery, even when normalizing for tumor size." (PMID 35048498, 2022). "Besides in vitro assays, we performed in vivo experiments to explore the impact of METTL14 on tumor metastasis." (PMID 36288387, 2022). "To further understand the role played by METTL14 in BlCa tumor growth, we performed the CAM assay." (PMID 35048498, 2022). "In addition, miR-3165 facilitates BC cell progression and tumor metastasis via down-regulating tumor suppressor METTL14." (PMID 36288387, 2022). "We also detected the effect of METTL14 on tumor proliferation." (PMID 35036065, 2022). "The expression of METTL14 was significantly related to the overall survival of PCa patients and to tumor stage T. Additionally, we found that the expression level of METTL14 is associated with disease status (Complete regression/relapse) according to ICGC datasets." (PMID 35559023, 2022).
tumor (continued). "Functionally, knocking down METTL14 inhibited tumor proliferation both in vitro and in vivo." (PMID 35354789, 2022). "Depletion of METTL3 or METTL14 in tumor cells increased cytotoxic tumor-infiltrating CD8+ T cells and elevated secretion of IFN-γ, CXCL9, and CXCL10 in the TME, thereby enhancing the response to anti-PD-1 treatment in mismatch-repair-proficient or microsatellite instability-low CRC tumors." (PMID 35296338, 2022). "In most tumors, METTL14 downregulates the m6A levels in cancer cells by acting as m6A methyltransferase to inhibit the occurrence and development of tumors, thereby playing an anti-tumor role." (PMID 36371254, 2022). "It is expected that METTL14 could become a novel molecule for tumor therapy, but the comprehensive study of METTL14 in CC is still unclear." (PMID 35777046, 2022). "Furthermore, patients with low expression of METTL14 showed poorer OS, suggesting that METTL14 plays a tumor-suppressor role in ccRCC." (PMID 35036065, 2022). "Moreover, the depletion of methyltransferases METTL3 and METTL14 in tumor cells is found to prominently induce the activation of the IFN-γ-STAT1-IRF1 signaling axis through the stabilization of the STAT1 and IRF1 mRNA via YTHDF2." (PMID 35693795, 2022). "For instance, METTL14 was initially identified as a tumour suppressor in HCC." (PMID 33461542, 2021). "Furthermore, METTL14 has proved to play a tumor-suppressive role in ultraviolet-induced skin tumorigenesis." (PMID 34988083, 2021). "We further confirmed that METTL14 as a tumor suppressor in the STAD cells." (PMID 34476213, 2021). "Endometrial cancer is associated with a METTL14 mutation (R298P), which results in decreased expression of the negative AKT regulator PHLPP2, increased expression of the positive AKT regulator mTORC2 and tumor cell proliferation." (PMID 33922187, 2021). "In breast cancer, METTL14 serves as an oncogene and drives tumor cell migration and invasion." (PMID 34122497, 2021). "Our findings indicate that METTL14 partakes in the biological process of GC as a tumor suppressor and may be an emerging biomarker in GC." (PMID 33314339, 2021). "METTL14 depresses GC cell progression and aggression as a tumor suppressor." (PMID 33314339, 2021). "We further examined whether inhibition of SLC7A11 contributes to the anti‐tumour effects of METTL14." (PMID 34609072, 2021). "The results showed that the volume and weight of subcutaneous tumours in the OEMETTL14 group were significantly lower than those in the OECtrl group, indicating that METTL14 overexpression can effectively inhibit the growth of OSCC subcutaneous tumours in mice." (PMID 34900689, 2021). "In addition, we conducted a univariate Cox analysis of the TCGA-KIRC cohort and found that age, tumor grade, pathological stage, T stage, metastatic status, and METTL14 level correlated significantly with 5-year OS." (PMID 33664855, 2021). "Similarly, Yang and colleagues reported that METTL14 down-regulated the expression of XIST lncRNA through the m6A-YTHDF2-dependent pathway to exert tumor suppressive effect." (PMID 33836813, 2021). "Specifically, downregulation of METTL14 expression could facilitate tumor metastasis, and METTL14 was verified to be a potential prognostic biomarker for indicating the metastasis of CRC." (PMID 34345203, 2021). "Furthermore, we constructed an in vivo metastatic model and observed that BPTF knockdown significantly suppressed the tumor metastatic ability of METTL14-/- cells, which were quantified and compared by the number or size of lung metastatic lesions." (PMID 33664855, 2021). "Decreased METTL14 is observed in HCC and closely associated with tumor metastasis and prognosis." (PMID 34272618, 2021). "We still lack studies of the correlation between METTL14 and tumor immunity." (PMID 34122497, 2021). "We speculated that the complex tumor microenvironment and the longer tumor growth time in vivo amplified the role of METTL14 on proliferation." (PMID 34916487, 2021).
tumor (continued). "By contrast, METTL14 was reported as a tumor suppressor gene in several studies." (PMID 34336824, 2021). "In this study, we indicated that METTL14 might act as a modulator of Tregs to regulate tumor immunity in ccRCC." (PMID 34122497, 2021). "Considering that tumor heterogeneity is a determinant of cancer progression and evolution, we questioned whether distinct METTL14 expression levels can influence the drug efficiency of AU1 in mRCC." (PMID 33664855, 2021). "In other tumours, METTL3 and METTL14 play an tumour suppressive role." (PMID 33461542, 2021). "In conclusion, these findings suggest that the METTL14/CCL5/Tregs axis is a potential signaling pathway for regulating tumor immunity, and might become novel therapeutic targets for ccRCC." (PMID 34122497, 2021). "Importantly, ectopic expression of SLC7A11 strongly blocked METTL14‐induced tumour‐suppressive effect in hypoxic HCC." (PMID 34609072, 2021). "METTL14 inhibits tumor growth and metastasis of STAD via stabilization of PTEN mRNA expression." (PMID 34476213, 2021). "METTL14 loss elevated tumor proliferation in vivo but have no obviously effects on proliferation of CRC cells in vitro." (PMID 34916487, 2021). "Combining this approach with tumor immune analysis, we found that METTL14 might suppress tumor progression through mediating Tregs." (PMID 34122497, 2021). "Furthermore, an in vivo tumour xenograft model confirmed that a high METTL14 expression can effectively reduce OSCC growth." (PMID 34900689, 2021). "Moreover, the pathways associated with tumor progression were investigated, which provides a potential molecular basis for YTHDC2 and METTL14 mediated RC development." (PMID 34149792, 2021). "However, the loss-of-function analysis in larger cohort of tumor cell lines indicated the biological importance of METTL3 and METTL14 in cancer cell growth and survival." (PMID 34285249, 2021). "METTL14-mediated m6A modification in tumor-associated macrophages (TAMs) were found to modulate tumor-infiltrating CD8+ T cells, since macrophage-specific knockout of Mettl14 drives CD8+ T cell differentiation along a dysfunctional trajectory, impairing CD8+ T cells to eliminate tumors." (PMID 34526985, 2021). "Meanwhile, overexpression of SLC7A11 could significantly rescue METTL14‐induced tumour‐suppressive effect under hypoxia in HCC." (PMID 34609072, 2021). "Notably, we observed that m6A “writers” METTL3 and METTL14 mRNA levels were respectively decreased by ~75% and ~49% in tumor-infiltrating NK cells of HCC patients." (PMID 34535671, 2021). "METTL14 expression showed a negative association with TGFβ1, which is known to promote tumor immune tolerance by upregulating PD1 expression on T cells." (PMID 34221955, 2021). "Conversely, depletion of METTL14 effectively suppressed tumor growth in these models." (PMID 32843065, 2020). "Notably, we observed that elevated METTL14 expression enhanced tumor growth in both subcutaneous and orthotopic transplantation models in nude mice." (PMID 32843065, 2020). "METTL14 is critical for EBV-associated tumorigenesis through interactions with viral-encoded latent oncoprotein EBNA3C, but in the majority of cases, it serves as a tumor suppressor in several types of cancer, including GBM, HCC, CRC, BCA and EC." (PMID 32513173, 2020). "Decreased METTL14 facilitates tumor metastasis in CRC, suggesting that METTL14 might be a potential prognostic biomarker and effective therapeutic target for CRC." (PMID 32552762, 2020). "Overexpression of METTL3 or METTL14 also promotes tumor progression in solid cancers." (PMID 32296573, 2020). "Only recently the expression profiles of 13 m6A-related genes in 317 OSCC and 32 normal samples from The Cancer Genome Atlas (TCGA) database had been analyzed and found a significantly higher expression of eight genes, including METTL3 and METTL14, in tumor tissues." (PMID 32957697, 2020).
tumor (continued). "Furthermore, the expression of IGF2BP1, METTL3 and METTL14 is strongly correlated with E2F1–3 expression (R = 0.4) across 33 TCGA tumor cohorts." (PMID 32761127, 2020). "However, METTL14 was found to act as both the tumor suppressor and the oncogenic protein by collaborating with different m6A “reader” proteins in the context of diverse cancer types." (PMID 33584787, 2020). "Moreover, we demonstrated that METTL14 downregulation resulted in enhanced tumor growth and invasion of CRC both in vitro and in vivo." (PMID 32111213, 2020). "Whether other factors, such as the tumor microenvironment, impact METTL14 function deserves further exploration." (PMID 33505967, 2020). "Remarkably, m6A seldom acts as a tumor-suppressor, excluding METTL14." (PMID 32513173, 2020). "Consistently, METTL3 serves as an oncogene, but METTL14 is a tumor suppressor in HCC." (PMID 33159022, 2020). "METTL3 is highly expressed in tumor tissues, while METTL14 expression is low." (PMID 32258108, 2020). "As shown, low expression of METTL14 was positively correlated with larger tumor size, lymphatic invasion, remote metastasis and more advanced TNM stage, indicating METTL14 might play an important role in modulating proliferation and invasion of CRC." (PMID 32111213, 2020). "Given the fact that METTL14 is down-regulated in tumor tissue, we speculated that METTL14 may act as a tumor suppressor in CRC." (PMID 32111213, 2020). "Gradient Mettl14 knockout cells were injected into BALB/c nude mice for tumor initiation." (PMID 31760940, 2019). "Increased tumor propagation was found in Mettl14 knockout cells." (PMID 31760940, 2019). "A previous study discovered that the “writers” of m6A methylation, METTL3 and METTL14, could play both oncogenic and tumor suppressor roles in numerous cancers, while oncogenic roles have been reported for “erasers” such as FTO and ALKBH5." (PMID 31722709, 2019). "Mettl14 deleted cells showed enhanced tumor formation ability." (PMID 31760940, 2019). "METTL14 had a positive correlation with the tumor suppressor gene PTEN, so we speculated that METTL14 exerted a tumor suppressor effect in KIRC by stabilizing PTEN mRNA." (PMID 31976022, 2019). "METTL14 has different expression levels in various tumor tissues." (PMID 31142332, 2019). "Meanwhile, Mettl14 overexpressing cells showed impaired role in tumor invasion and propagation." (PMID 31760940, 2019). "Additionally, depletion of METTL3 or METTL14 enhances tumor tumorigenicity while FTO inhibitor treatment prevents tumor deterioration." (PMID 30062093, 2018). "Compared to mice grafted with control cells, mice transplanted with PBT003 cells having METTL14 KD or METTL3 and METTL14 double KD developed much bigger tumors, as revealed by a dramatic increase in tumor luciferase activity at week 4, 5, or 6 after GSC transplantation." (PMID 28297667, 2017). "Furthermore, the silencing of METTL14 significantly increased the anti-tumor effects induced by oHSV-1, indicating that the METTL14/ISG15 pathway may serve as a promising therapeutic target for HSV-1 infections." (PMID 41019992, 2025). "We found that after inhibiting METTL14 expression, the circ_0060927 m6A modification level significantly decreased; conversely, overexpression of METTL14 could upregulate the circ_0060927 m6A modification level in tumor cells." (PMID 41323393, 2025). "When dissociated from METTL3, METTL14 may be more inclined to stabilize tumor suppressor RNA." (PMID 41256854, 2025). "However, there are instances where METTL14 has been shown to promote tumor growth." (PMID 40567896, 2025). "Furthermore, METTL14 knockdown has been associated with increased tumor immunogenicity, as evidenced by enhanced CD8+ T‐cell infiltration and elevated secretion of IFN‐γ and CXCL9/10 within the tumor microenvironment." (PMID 41316520, 2025).
tumor (continued). "Moreover, the integration of emerging concepts such as phase separation and 3D genome architecture may provide additional layers of regulatory insight, potentially guiding more precise manipulation of METTL14 in the tumor immune microenvironment." (PMID 41164187, 2025). "Likewise, the other m6A writer enzyme METTL14 exhibits tumor-type specific roles." (PMID 41301491, 2025). "In vivo experiments also showed that METTL14 knockdown could inhibit tumor formation and growth." (PMID 38326804, 2024). "Targeting “writers” such as METTL3 or METTL14 blocks the formation of m6A and thus can play a role in multiple tumor-suppressing or immune therapy-enhancing effects; however, this may also greatly impact normal physiological functions and lead to severe side effects." (PMID 39372415, 2024). "Furthermore, the mRNA half-life of G6PD was reduced in tumor cells with METTL14 downregulation." (PMID 39138186, 2024). "The most typical family member METTL3/METTL14 forms a methyltransferase complex involved in N6-methyladenosine (m6A) modification of RNA, regulating tumor proliferation, metastasis and invasion, immunotherapy resistance, and metabolic reprogramming of tumor cells." (PMID 37533128, 2023). "METTL14 could function as tumor suppressor of oncogenic factor during tumour progression." (PMID 38021156, 2023). "Moreover, other studies found that METTL14 significantly elevated the target gene miRNA126 by positively modulating the pri‐miRNA126 process, thereby playing a tumour‐suppressor role in hepatocellular carcinoma and eventually inhibiting tumour invasion and metastasis." (PMID 38082402, 2023). "Mettl14 knockdown in tumor‐associated macrophages in tumor microenvironment triggers CD8+ T cells differentiating toward a dysfunctional state in mouse models, thus impairing their ability to eliminate tumors, highlighting the tumor‐suppressive role of Mettl14 in tumor microenvironment." (PMID 36794620, 2023). "Furthermore, in vivo, METTL14 knockdown also reduces tumor size." (PMID 38117350, 2023). "Also, METTL14 was found to regulate the functions of immunomodulatory ligands in macrophages, and METTL14 deficiency in macrophage1919s inhibited the anti-tumor function of CD8 + T cells and promoted tumor growth." (PMID 36810281, 2023). "Additionally, depletion of METTL3/METTL14 sensitizes tumor cells to IFN‐γ treatment." (PMID 36810108, 2023). "Finally, we tested whether glycolysis plays a role in METTL14/miR‐6769b‐3p and METTL14/miR‐499a‐3p axis‐mediated regulation of tumor growth in vivo." (PMID 36794620, 2023). "It has been suggested that silencing METTL14 may inhibit tumor angiogenesis." (PMID 38053093, 2023). "We speculated that METTL14 serves as a tumour promoter in BCa." (PMID 36168624, 2022). "Notably, expression of the tumor suppressors METTL14 and ZC3H13 was positively correlated with the infiltration of Tcm cells, Th17 cells, and eosinophils, consistent with previous findings that these cells are associated with a favorable prognosis of malignant tumors." (PMID 35223847, 2022). "Finally we demonstrate the tumour-suppressive role of METTL14, a major RNA N6-adenosine methyltransferase (m6A), and illustrate that its loss-of-function mutation R298H may act through m6A modification on potential driver gene MACF1." (PMID 35650238, 2022). "However, METTL14, as a tumor suppressor in HCC, is down-regulated." (PMID 35784761, 2022). "Our results indicate that the anti‐tumour effect induced by METTL14 might be intervened by SLC7A11." (PMID 34609072, 2021). "In addition, whether METTL14 leads to the acquisition of other phenotypes, such as tumor immunity, stemness traits, or apoptosis in RCC is worth systematically elucidating." (PMID 33664855, 2021). "Moreover, decreased METTL14 protein was significantly correlated to tumor stage." (PMID 34916487, 2021). "Hence, METTL14 expression may be a potential prognostic marker of favorable survival and a tumor suppressor in ccRCC." (PMID 33430867, 2021).